PARP1 (poly(ADP-ribose) polymerase 1)
Diseases named in the same sentence as PARP1 in open-access papers (continued):
Sharing a sentence is not in itself a finding about the gene and the disease.
myopathy (1 paper, 2023). A disease of the muscle in which the muscle fibers do not function properly. "These indicate potential for PARP1 roles in the transcriptional pathways manifesting glucocorticoid-induced myopathy, necessitating broader studies." (PMID 37087471, 2023). "Furthermore, PARP1 has demonstrated involvement in myopathy, as does chronic glucocorticoid exposure." (PMID 37087471, 2023).
PARP1 also shares sentences with these, for which no sentence is quoted: Parkinson’s (9 papers); Ataxia (4); hyperlipidemia (4); malignant pleural mesothelioma (4); prostate adenocarcinoma (4); -Deficient (3); Barrett esophagus (3); idiopathic pulmonary fibrosis (3); memory impairment (3); pneumonia (3); animal disease (2); basal cell carcinoma (2); bladder tumor (2); fibrosarcoma (2); gallbladder carcinoma (2); Kidney Chromophobe (2); mucosal (2); myxofibrosarcoma (2); ovarian adenocarcinoma (2); peripheral neuropathy (2); premature aging syndrome (2); respiratory disease (2); Shock (2); tongue cancer (2); acute myocardial infarction (1); adenomyosis (1); adrenocortical carcinoma (1); adult fibrosarcoma (1); age-related macular degeneration (1); aneurysm (1).
A further 131 diseases each share a sentence with PARP1 in 1 paper.